TRHDE (thyrotropin releasing hormone degrading enzyme)
Description:
Specific inactivation of TRH after its release.
Synonyms: TRH-DE; PAP-II; PGPEP2
Tractability: Antibody: its Gene Ontology location is reachable by antibodies, with high confidence; UniProt predicts a signal peptide or a membrane-spanning region. PROTAC: a small molecule that binds it is known.
Target class: Enzyme; Hydrolase
Gene: Protein-coding gene on chromosome 12 (72,087,266 to 72,670,758, forward strand). Ensembl gene ENSG00000072657.
Subcellular location: Membrane
Gene Ontology:
Molecular function: aminopeptidase activity; metalloaminopeptidase activity; metallopeptidase activity; pyroglutamyl-peptidase activity; zinc ion binding
Biological process: cell-cell signaling; peptide catabolic process; proteolysis; signal transduction
Cellular component: extracellular exosome; plasma membrane; membrane
Genetic constraint (gnomAD): Loss-of-function variants: 46 observed, 73.92 expected, observed/expected ratio (o/e) 0.62, 90% interval 0.49 to 0.8. The upper end of that interval is the gene's LOEUF score, 0.8, which puts it in group 3 of 6, group 1 being the genes least tolerant of losing a copy. Missense variants: 801 observed, 924.57 expected, observed/expected ratio (o/e) 0.87, 90% interval 0.82 to 0.92. Synonymous variants: 384 observed, 366.46 expected, observed/expected ratio (o/e) 1.05, 90% interval 0.96 to 1.14.
Homologues: Orthologues: chimpanzee TRHDE (99% identical), macaque TRHDE (97% identical), pig TRHDE (95% identical), mouse Trhde (95% identical), rat Trhde (95% identical), rabbit TRHDE (92% identical), dog TRHDE (90% identical), tropical clawed frog trhde (74% identical), zebrafish trhde.2 (62% identical), zebrafish trhde.1 (62% identical), guinea pig TRHDE (58% identical), Drosophila melanogaster CG31445 (21% identical), and 13 more. Paralogues in human: ANPEP (24% identical), ENPEP (23% identical), ERAP1 (23% identical), ERAP2 (23% identical), LNPEP (23% identical), LVRN (22% identical), NPEPPS (21% identical), RNPEPL1 (13% identical), AOPEP (12% identical), RNPEP (12% identical), LTA4H (12% identical).
Diseases named in the same sentence as TRHDE in open-access papers:
TRHDE is named in the same sentence as 11 diseases in open-access papers, as found by Europe PMC text mining. Sharing a sentence is not in itself a finding about the gene and the disease. The quoted sentences say what the papers report.
glioma (2 papers, 2017 to 2022). A benign or malignant brain and spinal cord tumor that arises from glial cells (astrocytes, oligodendrocytes, ependymal cells). "FSTL5, HCN1, TMEM132D, TRHDE and KRT222 showed the strongest expression correlation with other genes in the co-expression network of glioma tissues." (PMID 29046615, 2017). "There are no studies on the role of TRHDE in NAFLD, but it has been reported in oral cancer, lung cancer, and glioma development, and its relationship with thyroid hormones could be explored in depth." (PMID 35910194, 2022).
breast carcinoma (1 paper, 2016). "Furthermore, there have been no reports on the activity of CLIP4, CAPN2, CRLF1, CYBRD1, PHF10, and TRHDE in breast cancer or chemoresistance, thus making them new candidates for understanding breast cancer, the EMT, and chemoresistance." (PMID 27094684, 2016).
oral cancer (1 paper, 2022). "TRHDE was reported to be a DNA methylation marker for precancerous lesions in oral cancer." (PMID 35910194, 2022).
ovarian carcinoma (1 paper, 2022). A malignant neoplasm originating from the surface ovarian epithelium. "Ovarian cancer patients with higher RNA levels of TPH2, DCN, TRHDE, and LUM have lower OS when compared with ovarian cancer patients with lower levels of these genes." (PMID 35008958, 2022).
TRHDE also shares sentences with these, for which no sentence is quoted: cancer (2 papers); acute promyelocytic leukemia (1); central nervous system disorder (1); Hypertension (1); immune system disorder (1); infectious disease (1); malaria (1).